GFAP (glial fibrillary acidic protein)
Diseases named in the same sentence as GFAP in open-access papers (continued):
Sharing a sentence is not in itself a finding about the gene and the disease.
tumor (continued). "The recurrent tumor contained GFAP‐expressing gliomatous tissue and reticulin‐rich sarcomatous elements." (PMID 34605602, 2021). "Immunofluorescence analysis shows a thin gap with GFAP expression delimiting the tumor and ependymal region." (PMID 34163334, 2021). "Similar to the supratentorial tumor cells, these tumor cells were positive for GFAP, SOX2, and ATRX." (PMID 34587990, 2021). "For the IHC analysis, we used GFAP as a marker of astroglial injury and we denoted that the simple process of GlioGel inoculation increased staining in the non-tumor bearing hemisphere." (PMID 34830041, 2021). "Tumor cells are strongly immunoreactive for a glial fibrillary acid protein (GFAP), Olig2, and S100." (PMID 34065573, 2021). "Quantification of the distribution of the staining for TNT-associated proteins, 14-3-3γ and GAP43, as well as PCNA and GFAP, indicates the exquisite distribution of all these components at the tumor-tissue interface." (PMID 34267246, 2021). "Vimentin expression was also increased in the tumor mass, whereas GFAP expression in the tumor mass was even slightly lower compared to its expression in the contralateral hemisphere." (PMID 34441246, 2021). "When the GlioGel is inoculated in the tumor, most of the marking for GFAP was at the periphery of the tumor." (PMID 34830041, 2021). "Elevated concentrations of GFAP in the blood correlate with tumor volume, intratumor GFAP expression, and the degree of necrosis." (PMID 34210107, 2021). "Immunohistochemical staining showed that the tumor cells were positive for glial fibrillary acidic protein and vimentin." (PMID 34713831, 2021). "The tumor mass covered most of the striatal area and was surrounded by GFAP+ astrocytes that were partially recombined." (PMID 34535655, 2021). "Compared with A375 cells, A375 xenograft tumor displayed an upregulation for glial and neuronal genes (GFAP, BDNF, MAP2, MTURN, ROBO2, SYT1 and TUBB3) and neural stemness genes (ASCL1, MSI1, PAX6, PDGFRA, SOX9, VIM, ZIC1/2)." (PMID 33468253, 2021). "In this case, for example, glial and neural markers (glial fibrillary acidic protein, S100, or synaptophysin) were positively expressed by the donor tumor cells but were undetected in the recipient lesions." (PMID 34301805, 2021). "Dense GFAP and vimentin labeling in the brain parenchyma surrounding the tumor mass reflect the presence of reactive astrocytes." (PMID 34441246, 2021). "We observed a higher Cx43 expression in GFAP-expressing cells localized further from metastases than those closer to the tumor." (PMID 33671551, 2021). "We additionally performed DNA-methylation profiling from only GFAP positive glial appearing tumor components of eight cases." (PMID 33876327, 2021). "Peritumoral areas surrounding tumor nodes showed highly reactive protoplasmic GFAP-positive astrocytes, which were gradually reduced when approaching the tumor-free cortex." (PMID 34771741, 2021). "In the tumor group, the fluorescence intensity of GFAP in the tumor area was significantly higher, whereas the fluorescence intensity of AQP4 was significantly weaker." (PMID 35083148, 2021). "The GFAP-positivity of the tumour and the timing of the blood sampling, before or during surgery did not affect GFAP+CD16+ monocytes." (PMID 33501422, 2021). "Overall, GFAP IHC revealed the presence of GFAP expressing cells surrounding the tumor with a morphology typical of astrocytes." (PMID 33500706, 2021).
tumor (continued). "As vimentin expression is an early event in normal glial differentiation, while GFAP only appears in later stages, this indicates that the majority of tumor cells in these GB tumors were neoplastic astrocytes in a dedifferentiated state." (PMID 34441246, 2021). "WT1, COL11A1, FGF5, and IGFL2 were up-regulated in tumor tissues, while GFAP and CD300LG were down-regulated." (PMID 33987034, 2021). "In the glioneuronal components, the astrocyte‐like tumor cells were positive for GFAP and the neurocyte‐like tumor cells were positive for synaptophysin." (PMID 33576087, 2021). "The microscopy of AG exhibited tumor cells arranged around vessels shaped like clumped chrysanthemums, and tumor cells were strongly and diffusely positive for GFAP and Nestin." (PMID 32058680, 2020). "The intensities of Tubilin α1-A and GFAP have the same standard deviation in the normal region as in the tumour region, and the mean value is higher in the normal region." (PMID 32238824, 2020). "The average intensities of Tubulin β-2A, Tubulin α-1A and GFAP (m/z 1208) were lower in the metastatic tumour region than in the normal region (small)." (PMID 32238824, 2020). "Fluorescence images also showed that CTCs captured by GFAP-IMLs from the blood and tumor tissues of nude mice were similar in cell morphology to U87-GFP cells with spontaneous green fluorescence." (PMID 33208163, 2020). "The advancing tumor incorporates reactive astrocytes either as round cells or as GFAP-positive multipolar, spindle, or gemistocytic cells, with long processes on vessels." (PMID 32599896, 2020). "The first intracranial injection indicated a global GFAP reaction throughout the brain very similar to the tumor morphology in the patient sample." (PMID 32698368, 2020). "Accordingly, down-regulation of SPP1 reduced tumor cells invasion and vimentin expression, but increased the level of GFAP, a marker of differentiated astrocytes." (PMID 33066172, 2020). "The lung biopsy showed a heterogeneous tumor with diffuse GFAP expression, that exhibited areas of pleomorphic cells embedded in a myxoid extracellular matrix showing brisk mitotic activity, and areas of fibroblastic-like cells with lower mitotic activity." (PMID 32014051, 2020). "Although scattered GFAP-positive cells were detected within the tumor, the bulk of tumor was devoid of astrocytes, in line with previous findings with this model." (PMID 32190011, 2020). "Immunofluorescence showed that these tumor spheres were able to differentiate into GFAP+ astrocytes, MAP2+ neurons, and O4+ oligodendrocytes." (PMID 32843056, 2020). "We measured the intensity of the signals of Histone H2A, Histone H4, Histone H2B, Tubulin β-2A, Tubulin α-1A and GFAP (m/z 1208) in each ROI (sample 1 tumour: N = 369, normal: N = 730; sample 3 tumour: N = 532, normal: N = 231)." (PMID 32238824, 2020). "Among ALDH1A3 positive cells, there were some GFAP positive cells likely reactive astrocytes or tumor cells due to their distinct morphology." (PMID 32680476, 2020). "Double immunofluorescence staining revealed a co-localization of ALDH1A3 with GFAP in glial-shaped cells and in tumor cells." (PMID 32680476, 2020). "Excessive reactive astrocytes were commonly observed in the tumors as shown by extensive immunopositivity for GFAP adjacent to the HA-positive tumor cells." (PMID 33228790, 2020). "Vimentin and GFAP labeling are both dense at the tumor border, where these cells display a palisade arrangement in their cell processes." (PMID 32977526, 2020). "Histopathological examinations on tumor sections showed DCXNLS2-mut tumor tissue displayed less amount of Vimentin and GFAP staining compared with DCX-vector via IHC." (PMID 32050972, 2020). "Higher serum GFAP levels correlate with tumor volumes, intra-tumoral GFAP expression, and extent of necrosis." (PMID 32650387, 2020).
tumor (continued). "Co-immunofluorescene staining demonstrates on a cellular level, that Mib1-positive tumor cells express glial fibrillary acidic protein only very sporadically." (PMID 32391260, 2020). "The positivity for GFAP and the cytogenetic characteristics demonstrate the glial and tumor profile of the three primary cultures." (PMID 33396457, 2020). "The last passage had similar GFAP astrogliosis to the tissue from the primary resection (patient parental tumor) which demonstrated moderate gliosis." (PMID 32698368, 2020). "Further, the glial fibrillary acidic protein (GFAP) staining also indicated increased astrogliosis surrounding the tumor with each passage." (PMID 32698368, 2020). "In contrast to MCT1, GFAP showed a statistically significantly increased expression at the tumor edge compared with the center." (PMID 32872409, 2020). "Dense GFAP labeling in the brain parenchyma surrounding the tumor reflects the presence of reactive astrocytes." (PMID 32977526, 2020). "Histological features such as nuclear polymorphisms were much more frequent in children as compared to GFAP-positive tumor cells that were sensitive markers for adult MB." (PMID 32226663, 2020). "All tumours showed cells with enlarged, pleomorphic and occasional hyperchromatic nuclei on H&E, whilst all conditions show diffuse staining for GFAP (cytoplasmic) and SOX2 (nuclear), with a smaller fraction positive for OLIG2." (PMID 31988455, 2020). "The third 2025 passage through a mouse had a more localized GFAP gliosis reaction responding to tumor engraftment." (PMID 32698368, 2020). "Quantitative analysis of the frequency of GFAP+/S100+ SCs detected in the tissue slides demonstrated that SCs were more abundant in the PDAC tumor microenvironment compared with that in the adjacent NP." (PMID 32308766, 2020). "RNA scope analysis at PID9 showed high levels of GFAP mRNA around the area of dense tumor cells in GB rats." (PMID 32977526, 2020). "Serum GFAP levels associated with primary and recurrent high-grade glioma (HGG) tumor volumes and short PFS progression free survival (PFS)." (PMID 32650387, 2020). "Vimentin was profuse in tumor tissue and at the tumor border, whereas GFAP staining was only profuse at the tumor border and more heterogeneously expressed throughout the tumor." (PMID 32977526, 2020). "In contrast, GFAP staining of reactive astrocytes showed a strong signal in the peritumoral area in all tumor models in congruence with the prominent spherical binding of 68Ga-PSMA and 18F-DCFPyL." (PMID 32451793, 2020). "RNAscope results showed that GB tumors are surrounded by reactive gliosis reflected by the high level of GFAP mRNA surrounding the dense tumor core." (PMID 32977526, 2020). "The fibrillary background and tumor cell process toward perivascular pseudorosettes can be highlighted by the biomarker of the glial lineage tumor, GFAP." (PMID 33271970, 2020). "The U251 and U87 cells in the tumor model were immunostained with GFAP after 72 h of incubation and imaged by confocal microscopy." (PMID 32365781, 2020). "Well in line with histology, the tumor showed expression of both glial (e.g. GFAP) and neuronal markers (e.g. synaptophysin) with pathological expression of CD34 and retained ATRX expression." (PMID 32451719, 2020). "Positive GFAP immunohistochemical staining can be found in the tumor area, confirming that the tumor tissues were astrocytic origin." (PMID 31551769, 2019). "Immunohistochemical examination showed that the tumor cells were positive for Vimentin, GFAP, CD56, ER, and PR." (PMID 31689791, 2019). "Another entry in this group is the WHO grade pilocytic astrocytoma - a tumor with astrocytic glial differentiation, presenting as a pilocytic rich, GFAP positive lesion, predominantly in the pediatric population." (PMID 31938662, 2019).
tumor (continued). "Glial fibrillary acidic protein (GFAP), vimentin, Ki67, S100 protein, neurofilament immunoreactivity were detected in the tumor produced on the CAM and infiltration of macrophages (CD68) and T cells (CD3+, CD8+) was observed." (PMID 31083409, 2019). "Next, we seeded the purified DRG axons with hGCs, which exhibited extensive interactions with the unmyelinated DRG axons, integrated within the axonal network and formed GFAP+/Ki67+ tumor-like structures." (PMID 30353164, 2019). "pERK IHC staining revealed clear co-expression with the GFAP+ glial-predominant tumour regions which also showed less proliferation as shown by very low level Ki67 staining." (PMID 31463571, 2019). "Further investigations are needed to dissect the relative contribution of GFAP and Tau released from adjacent tissue injury versus direct tumor release." (PMID 31311947, 2019). "We also observed this phenomenon in patient tissue, where more differentiated, GFAP+ Ki67low vimentinlow, tumour regions stained positive for phosphorylated ERK1/2, highlighting an active process during disease progression." (PMID 31463571, 2019). "In this context, it is highly likely that injury to the brain secondary to mass effect of a growing tumor contributes to the elevation in plasma EV-contained GFAP and Tau." (PMID 31311947, 2019). "The tumor cells composed of perivascular pseudorosettes showed positivity for both synaptophysin and glial markers such as GFAP and Olig2." (PMID 31804365, 2019). "The expression of the tumor glial marker GFAP and the neural marker Nestin were maintained in MNL and NS cultures for early passages, while long-term cell expansion partially lost the markers’ expression." (PMID 31779235, 2019). "Immunohistochemical analysis for the expression of human GFAP confirmed the glial origin of tumor, Ki67 detection shown high number of cycling cells in tumor tissue and high expression of vascular endothelial growth factor (VEGF) in tumor." (PMID 31292491, 2019). "We found pacritinib treatment suppressed cell viability and colony/tumor sphere formation in association with decreased expression of STAT3, Sox2, PDCD4, and miR-21-5p and increased GFAP expression." (PMID 31269723, 2019). "In accordance with previous reports, IHC with GFAP revealed a dense population of reactive astrocytes in the peri tumoral region and around the blood vessels in control tumor section." (PMID 30899038, 2019). "The correlation of CAIX staining with astrocyte activation marker, glial fibrillary acid protein (GFAP), at the tumor edge indicated the involvement of astrocyte activation on the development of peripheral hypoxia." (PMID 31106146, 2019). "The positive reaction for GFAP was consistent with the glial origin of the analyzed GBM tumor samples." (PMID 29912993, 2018). "Compared to the original tumor, R2J cells in culture (2D and spheres) lost the GFAP and CD56 expressions (only 2D) whereas Ki67, vimentin and nestin expressions were conserved as well as mesenchymal shift markers, such as CD44." (PMID 30583471, 2018). "Immunohistochemical staining showed GFAP-positive expression in both tumor cells and normal glial cells." (PMID 30285781, 2018). "Co-expression of PGP 9.5, NSE, calretinin, and GFAP in the tumor cells and normal nerve cells was observed in all cases." (PMID 29329562, 2018). "The tumor cells expressed variable levels of the astrocytic marker glial fibrillary acidic protein (GFAP), and expression of the neuronal marker NeuN was absent." (PMID 30082792, 2018). "Future research can test using JCPyV VLPs to package a GFAP promoter–driven therapeutic gene to target circulating tumor cells or overt extraneural metastases in patients with GBM." (PMID 29396437, 2018). "This increase in permeation resulted in increased uptake of chemotherapeutic agents and increased the expression of GFAP in regions adjacent to tumor, indicating reactive astrocytosis." (PMID 30526520, 2018).
tumor (continued). "Other biomarkers that help identify tumor source are cytokeratin, epithelial membrane antigen, glial fibrillary acidic protein (GFAP), and CgA." (PMID 30250431, 2018). "The tumour cells were positive for vimentin and exhibited patchy positive staining for GFAP and S-100, as well as focal positivity for EMA." (PMID 29348602, 2018). "Astrocytes undergo “reactive gliosis” in response to many CNS pathologies—such as trauma, tumor, or neurodegenerative disease, which is characterized by hypertrophy and a marked increase in GFAP expression." (PMID 30404643, 2018). "Immunohistochemical analysis for GFAP confirmed tumor formation originated in the glia (B5) and vascular proliferation (Fig. 4B6)." (PMID 30413179, 2018). "GFAP immunostaining specifically in the hippocampus also showed a marked intensity increase by day 11 after tumor cell implantation that remained intense at day 17 further confirming astrocyte activation." (PMID 30439993, 2018). "Following temozolomide chemotherapy, levels of the tumor marker GFAP were increased in the group with ultrasonic cavitation compared with the control group (P < 0.05)." (PMID 30534564, 2018). "We examined the effect of acoustic cavitation on temozolomide therapy efficacy by measuring tumor volume and testing GFAP and Ki-67 expression." (PMID 30534564, 2018). "Immunostaining for GFAP is positive, lending support to the theory that the tumor cell is derived from an astrocyte cell line." (PMID 29678196, 2018). "GFAP mRNA expression in tumor tissues in the test group was also increased relative to that in the control group." (PMID 30534564, 2018). "In order to discriminate tumor cells from fibroblasts in ring co-culture experiments several markers were tested including glial fibrillary acidic protein (GFAP) which did also stained fibroblasts in accordance with observations made by others." (PMID 30123089, 2018). "In vivo, the FK506/Vincristine treatment decreased the tumor size as well as ki67, Glial Fibrillary Acidic Protein (GFAP), and nestin expression." (PMID 30208561, 2018). "Flow cytometric analyses showed that 76.9% of EPN cells expressed GFAP, a tumor glial marker, while 5.5% showed positive staining for CD133, and an important percentage (99.4%) of these cells also expressed CD90." (PMID 29774098, 2018). "Western blot and immunocytochemistry analyses showed greater GFAP protein expression in the tumor tissues of the test group than in the control group." (PMID 30534564, 2018). "H-Ras, Ki67 and βIII-tubulin expression showed clear borderlines; however, GFAP expression was high in both the tumor and the adjacent normal tissue." (PMID 28199986, 2017). "Second, while the majority of patient tumor cells (>95%) were strongly positive (+++) for GFAP, a marker of mature/differentiated glial cells, there was a steady decrease of GFAP+ cells in PDOX tumors (26-50%)." (PMID 29152094, 2017). "Overall, these neoplasms appear to be generally composed of a ‘core’ expressing few biomarkers surrounded by a region of nestin- and GFAP-positive cells with small numbers of neurons interspersed throughout the two." (PMID 28493990, 2017). "We also verified the same pattern for nestin and GFAP for the cell lines when they formed tumor spheres." (PMID 28148893, 2017). "Another possibility is the use of gold NPs targeting brain markers, such as glial fibrillary acidic protein, to facilitate brain penetration, and deliver siRNA to knockdown tumor survival and proliferation genes." (PMID 28408882, 2017). "Well-differentiated tumour cells exhibit a moderate increase in the number of nuclei, variable nuclear pleomorphism, and a mesh-like network of glial fibrillary acidic protein (GFAP) processes." (PMID 29099032, 2017). "We found that all GBM cells expressed the tumor marker GFAP, and some expressed MMP-2 and TIMP-1 both in their cytoplasm and membrane." (PMID 28234925, 2017).